LRP1 (LDL receptor related protein 1)
Diseases named in the same sentence as LRP1 in open-access papers (continued):
Sharing a sentence is not in itself a finding about the gene and the disease.
migraine (continued). "Given LRP1’s role in maintaining blood-brain barrier integrity and its involvement in neuroinflammatory responses, this variant could potentially disrupt these processes, contributing to migraine pathophysiology." (PMID 40869943, 2025). "The association of modules A–E with migraine may be the result of low migraine association signals, and may therefore not have a direct link to the genome-wide significant GWAS loci, as only module B (LRP1) and module D (UFL1) contain a high-confidence gene." (PMID 26899160, 2016). "In our study, substantially elevated SNP-based heritability and replicable top hits in risk loci of PRDM16, FHL5, ASTN2, STAT6/LRP1, SLC24A3 genes were found among migraine-first patients." (PMID 39333847, 2024). "Our results provided new information on two of the strongest known migraine risk loci by estimating PIPs of 1.00 for the intronic variants rs9349379 in PHACTR1 and rs11172113 in LRP1." (PMID 39371129, 2024). "The resulting subnetwork included 9 genes: migraine-associated genes APOE, LRP1, CARF, CTIF, RNF213, and ECM1; LAMA2, which is associated with vestibular anomalies in mice; and the neurodevelopment-associated genes MYO5A and KLC2." (PMID 37107589, 2023). "One theory about its possible link with migraine is that the LRP1 protein interacts with the glutamate receptors on neurons while the pathophysiology of migraine has been suggested to be related with the glutamate homeostasis." (PMID 36939796, 2023). "The majority of the identified variants were found in genes previously associated with migraine (LRP1, ECM1, CARF, CTIF, RNF213, APOE, SLC35D2), with two different rare LRP1 variants each identified in two unrelated children with vertigo." (PMID 37107589, 2023). "Earlier GWAS identified migraine susceptibility SNPs nearby genes with mainly putative or known neuronal functions, including MTDH, PRDM16, TPRM8 and LRP1." (PMID 31226929, 2019). "In that study, two additional established migraine risk variants, rs11172113 in LRP1 and rs13208321 in FHL5, showed suggestive evidence for association to cervical artery dissection, with the same effect direction as for migraine." (PMID 28957430, 2017). "Multiple GWAS studies have proposed genes (PRDM16, TRPM8 or LRP1) and locus (Chr8q22.1) to be involved in the migraine." (PMID 24974787, 2015). "Five loci met stringent significance for association with migraine, among which four were selective for sub-classified migraine, including rs11172113 (LRP1) for MO." (PMID 24852292, 2014). "One of the most notable findings was the LRP1 p.Thr4077Arg (c.12230C>G) variant, which was observed in 3 out of 184 hemiplegic migraine patients (MAF = 0.008), compared to MAF = 0.00077 in the Non-Finnish European (NFE) population." (PMID 40869943, 2025). "LRP1 (PoPS Score Overall: 3.67, MO: 0.80), a lipoprotein receptor critical for blood-brain barrier integrity, showed significant overlap between Overall migraine and MO." (PMID 40826382, 2025). "Furthermore, the subtype analysis in this meta-analysis concluded that migraine without aura (MO) was significantly associated with seven genetic loci: near TSPAN2, TRPM8, PHACTR1, FHL5, ASTN2, FGF6, and LRP1." (PMID 39850553, 2024). "Also, a protective role of the LRP1-rs11172113variant was observed for both migraine and its clinical subtype i.e., MA (allelic model: OR of 0.65 [0.50–0.83] I2 = 44% and allele: OR: 0.54 [0.37–0.78], I2 = 52%) respectively." (PMID 37925562, 2023). "Considering that elevated interictal glutamate levels have been found in the visual cortex of patients with MA, cortical hyperexcitability may be among the pathophysiological mechanisms that connect LRP1 with migraine." (PMID 35454329, 2022). "Whereas seven loci (i.e. near TSPAN2, TRPM8, PHACTR1, FHL5, ASTN2, near FGF6, and LRP1) were associated with migraine without aura (in a sample of 8348 cases and 139,622 controls), none were associated with migraine with aura (6332 cases vs. 144,883 controls)." (PMID 32503413, 2020).
migraine (continued). "Several genes (MTDH, LRP1, MEF2D) identified by GWAS hits for common migraine could also be linked to glutamate signalling, although these genes are not part of modules A or C." (PMID 26899160, 2016). "For example, SNP rs1172113 (LRP1) was preferentially associated with the migraine without aura, i.e. MO (“inverse subset”), and also for migraine with duration 4–72 hours (“subset”)." (PMID 24852292, 2014). "While rs2651899 (PRDM16), rs10166942 (TRPM8), and rs11172113 (LRP1) appear most important for common migraine (i.e., at the population level), rs1835740 may play the major role in more severe forms of migraine (i.e., clinic-based populations)." (PMID 22072275, 2012). "Eleven polymorphisms, rs4759276, rs4759275, rs1385526, rs1799737, rs1466535, rs10876964, rs4759045, rs10876965, rs11172113, rs4367982, rs4759277 of the LRP1 gene showed significant results for migraine with p-values below the multiple hypothesis correction threshold of 3.66 × 10–6 (0.05/13635)." (PMID 40350427, 2025). "Finally, we did not detect any association between the LRP1 rs11172113 and any of the migraine phenotypes." (PMID 35454329, 2022). "Additionally, we did not detect any association between the LRP1 rs11172113 and any of the migraine phenotypes." (PMID 35454329, 2022). "Furthermore, the association between migraine and rs10166942 in transient receptor potential melastatin 8 (TRPM8) as well as rs1172113 in low density lipoprotein receptor-related protein 1 (LRP1), the two most replicated SNPs in Caucasians, were also reproduced in our study cohort." (PMID 31842742, 2019). "Finally, the associations seen for rs2651899 (PRDM16) and rs10166942 (TRPM8), but not rs11172113 (LRP1), were significantly associated with migraine compared to non-migraine headache, underlining the specificity of these variants for migraine." (PMID 22072275, 2012). "Notably, our study did not detect any association between migraine and LRP1 rs11172113." (PMID 35454329, 2022). "Loci mapping to the END1/PHACTR1, LRP1, and FHL5 genes in particular are shared by migraine and CAD or cervical artery dissection." (PMID 32632093, 2020). "Since our results are of GWAS significance, the genes (such as LRP1 and FHL5) identified for migraine by other GWAS are also promising candidate genes for tension-type headache." (PMID 29397368, 2018). "For cervical artery dissection, there also appears to be overlap with migraine at two more loci (LRP1 and FHL5), suggesting the possibility of partially shared genetic components between migraine and these diseases." (PMID 27543003, 2016). "Future challenges should be a GWAS in VM patients, since this is a subtype of migraine patients to define endophenotypes and a fine mapping analysis of MTDH, TRPM8 and LRP1 genes in VM." (PMID 22379397, 2011). "However, through an exploration of molecular changes in LRP1 knockout iPSC-SMCs, we observed several alterations particularly relevant to the pathogenesis of FMD, arterial dissection, migraine, and lung function." (PMID 39355906, 2024). "The associations of six SNPs identified from our previous study, including TRPM8 rs10166942, LRP1 rs1172113, DLG2 rs655484, GFRA1 rs3781545, UPP2 rs7565931, and GPR39 rs10803531, and migraine endophenotypes, including chronic migraine and allodynia were tested." (PMID 31842742, 2019). "Recently, genome-wide studies have provided new insights for genes associated with migraine disease (the ion channel gene, TRPM8, FHL5, ASTN2, and LRP1 but UTS2 gene was not one of them." (PMID 27090416, 2016). "LRP1 is a member of the lipoprotein family which modulates synaptic transmission and co-localizes with NMDA receptor in neurons, supporting that glutamate homeostasis is relevant in the pathophysiology of migraine." (PMID 22379397, 2011).
migraine (continued). "Second, some SNPs show no selectivity (i.e. “basic” model) for migraine attack frequency ≥6/year but selectivity (i.e. “subset” or “inverse subset” models) for other characteristics, for example aura status (rs11172113 [LRP1], rs6478241 [ASTN2], rs13208321 [FLH5], rs10504861 [near MMP16])." (PMID 24852292, 2014). "However, the 2016 finding by no means suggests that a neuronal origin of migraine is now excluded, already because at least five genes (PRDM16, MEF2D, FHL5, ASTN2, LRP1) (also) have a neuronal function." (PMID 30634909, 2019).
Obesity (29 papers, 2009 to 2025). Accumulation of substantial excess body fat. "Both obesity and alcohol intake have been linked to AD and our data suggests that liver steatosis associated with these two conditions modulates hepatic LRP1 and APP to disrupt Aβ processing by the liver to promote AD." (PMID 36187787, 2022). "In the hypothalamus, LRP1–/– mice exhibit obesity associated with hyperlipidemia, glucose intolerance, and insulin resistance, with similar phenotypes observed in neuronal LPL-deficient mice." (PMID 36590920, 2022). "The most significant finding of our work was that chronic alcohol feeding or obesity causes a major decline in hepatic LRP1 levels while substantially increasing hepatic APP levels." (PMID 36187787, 2022). "The impairment of LDL receptor-related protein-1 (LRP1) in numerous cell types is associated with obesity, diabetes, and fatty liver disease." (PMID 33500241, 2021). "The current study was undertaken to determine a potential role of macrophage LRP1 in obesity-associated inflammation." (PMID 30524198, 2018). "Although these tissue-specific knockout studies have provided us enormous information of Lrp1 functions and linked it to lipid metabolism, glucose homeostasis and obesity, the underlying mechanisms remain elusive." (PMID 28393867, 2017). "NYGGF4 is not well studied but appears well situated to mediate the effects of LRP1 on aspects of obesity, glucose tolerance, and cardiovascular risk factors." (PMID 20205790, 2010). "The fact that both alcohol feeding models (intragastric to mice and rats, NIAAA binge) and obesity caused the downregulation of LRP1 and upregulation of APP suggests that steatosis may be the uniting factor in the dysregulation of these two genes in the liver." (PMID 36187787, 2022). "In addition, LRP1 regulates the leptin/leptin receptor complex in the hypothalamus, with depletion in neuronal LRP1 being associated with increased food intake, and the subsequent increased risk of obesity and diabetes." (PMID 34945282, 2021). "Although LRP-1 has been shown to be upregulated in obese human adipose tissue, and increased concentrations of TGRL, such as chylomicron remnants, have been implicated in obesity in humans, this is the first study, to our knowledge, to report an association between LRP-1 variants and BMI in humans." (PMID 22347399, 2012). "Previous studies showed that adipocyte-specific LRP1 inactivation in mice reduces diet-induced obesity and glucose intolerance but results in hyperlipidemia due to impaired clearance of triglyceride-rich lipoproteins." (PMID 33500241, 2021). "In contrast, LRP1 inactivation in hepatocytes exacerbates HF diet-induced obesity, glucose intolerance, insulin resistance, and hepatosteatosis." (PMID 33500241, 2021). "Deletion of the Lrp1 gene in the mouse hypothalamus results in increased body weight (obesity); conditional Lrp1 brain knock-out produces glucose intolerance." (PMID 32655497, 2020). "LRP1 is a factor involved in lipid homeostasis and it has been shown to be overexpressed in adipose tissue in obesity and to control intracellular cholesterol storage and fatty acid synthesis." (PMID 30642114, 2019). "This study is, to our knowledge, the first to report that Lrp1 is a co-activator of Pparγ and that depletion of Lrp1 in endothelium regulates global energy homeostasis and alleviates some metabolic syndromes, such as obesity and insulin resistance." (PMID 28393867, 2017). "Mice with endothelial-specific Lrp1 deletion display improved glucose sensitivity and lipid profiles combined with increased oxygen consumption during high-fat-diet-induced obesity." (PMID 28393867, 2017). "Lipoprotein receptor LRP1 play critical roles in lipid metabolism, and this study reveals a novel role for LRP1 in controlling food intake and obesity in the central nervous system of the adult mouse." (PMID 21264353, 2011).
Obesity (continued). "In ConvR HFD mice liver, 17 genes DNA methylation changes including Ube2l3, Etv5, Lrp1, and Nudt3 were determined related to obesity and 11 genes DNA methylation changes including Exoc312, Mst1r, Prkch, and Arhgap26 were determined related to Type 2 diabetes (T2D) in the previous study." (PMID 35458198, 2022). "The underlying mechanism by which LRP1 dysfunction promotes obesity, diabetes, and fatty liver disease is not completely understood." (PMID 33500241, 2021). "Considering both APOA4 and LRP1 are multifunctional players in lipid and glucose metabolism, our finding opens up a door to better understand the molecular mechanisms along APOA4-LRP1 axis, whose dysregulation leads to obesity, cardiovascular disease, and diabetes." (PMID 34168225, 2021). "As LRP1 is abundant on the surface of hepatocytes, we hypothesized that PAI-1 activates CREB1 through LRP1-PKA–mediated signaling to increase tPA expression in obesity." (PMID 32657780, 2020). "Together, these data provide support for a pathway in which the increase in hepatocyte PAI-1 in obesity, mediated at least in part by suppression of Rev-Erbα, activates an LRP1/PKA/p-CREB/PLAT pathway that lessens the magnitude of the PAI-1–mediated decrease in fibrinolysis in obesity." (PMID 32657780, 2020). "First, we evaluated the role of endothelial Lrp1 in a HFD-induced obesity model." (PMID 28393867, 2017). "The LDL receptor-related protein-1 gene (LRP-1) has been associated with obesity in animal models, but no such association has yet been reported in humans." (PMID 22347399, 2012). "Mice with an adipocyte-specific inactivation of Lrp1 displayed delayed postprandial lipid clearance, reduced body weight, smaller fat stores, improved glucose tolerance, and resistance to dietary fat-induced obesity and glucose intolerance." (PMID 22384159, 2012). "Hence, LRP1 represents a very promising new therapeutic target for the design of innovative and more effective therapies for obesity." (PMID 21264353, 2011). "Murine studies with adipocyte-specific inactivation of the LRP1 gene have shown that LRP1 expression in these cells plays an important role in obesity development since these mice displayed a delayed postprandial lipid clearance and were resistant to diet-induced obesity." (PMID 21966368, 2011). "Genetic and functional studies have implicated both LRP1 and NYGGF4 in obesity and cardiovascular disease and the physical association of these proteins may reflect a common mechanism." (PMID 20205790, 2010). "The crucial role of LRP1 in obesity is also supported by a recent study showing that adipocyte LRP1−/− mice have an overall decrease in fat mass and are protected from high-fat diet-induced obesity." (PMID 19823686, 2009). "Altogether, our findings highlight the dual role of LRP1 in the control of adipogenesis and lipid homeostasis, and suggest that LRP1 may be an important therapeutic target in obesity." (PMID 19823686, 2009). "Adipose-specific LRP1-knockout mice generated by crossing LRP1flox/flox mice with aP2-Cre transgenic mice recently revealed its prominent role in lipid assimilation affecting energy metabolism and diet-induced obesity in mature adipocytes." (PMID 19823686, 2009). "Our experiments further show that silencing of LRP1 in fully-differentiated adipocytes significantly reduces cellular lipid content, suggesting that LRP1 may be an important therapeutic target in obesity." (PMID 19823686, 2009). "Our study highlights, for the first time, that LRP1 expression is up-regulated in obese human tissue, and suggests that this receptor may be an interesting therapeutic target in obesity." (PMID 19823686, 2009). "Altogether, these observations strongly suggest that a deregulation of LRP1 expression may have important consequences in adipocytes and obesity." (PMID 19823686, 2009).
Obesity (continued). "In a similar vein, disruption of LRP1 in adipocytes led to a delayed postprandial lipid clearance, reduced body weight, smaller fat stores, lipid-depleted brown adipocytes, and improved glucose tolerance, while showing resistance to dietary fat-induced obesity and glucose intolerance." (PMID 20205790, 2010). "Altogether, these findings highlight, for the first time, the crucial role of LRP1 in controlling adipogenesis and maintaining the lipid content in fully-differentiated adipocytes, and suggest that LRP1 may be an important therapeutic target in obesity." (PMID 19823686, 2009). "Interestingly, our in vitro study in 3T3F442A cells indicates that LRP1 expression is required for adipocyte differentiation and since LRP1 is abundantly expressed in adipocytes, we propose that LRP1 may participate in the onset of obesity." (PMID 19823686, 2009). "Therefore, we propose that LRP1 targeting in obesity may lead to a reduction of hypertrophic and hyperplasic adipocytes." (PMID 19823686, 2009). "In the early stages of obesity, ligand–receptor interactions involving LPL, LRP1, and ApoE in ATM contribute to lipid signaling, which regulates inflammation and shapes the metabolic microenvironment of adipose tissue." (PMID 40244284, 2025). "Spatial analyses further support pre-LAM localization to CLSs in early obesity and suggest pre-LAM signaling through App, Apoe, Lpl, and Lrp1 as drivers of CLS formation." (PMID 37651193, 2023). "Clearly, further studies will be needed to characterize the signaling pathways that modulate hepatic LRP-1 and APP in alcohol-induced and obesity-induced liver steatosis." (PMID 36187787, 2022). "In this study, we have studied the metabolic phenotype of endothelial Lrp1 knockout mice at basal condition and during high-fat-diet (HFD)-induced obesity." (PMID 28393867, 2017). "Our results indicate that the greater the degree of obesity the lower the gene expression of genes related with lipid processing in adipose tissue (LPL, FABP4, ASP and LRP1), both visceral and subcutaneous, though more obviously in the VAT." (PMID 21966368, 2011). "Until now, the implication of LRP1 in obesity has not been reported yet in human." (PMID 19823686, 2009).